MTOR (mechanistic target of rapamycin kinase)
Diseases named in the same sentence as MTOR in open-access papers (continued):
Sharing a sentence is not in itself a finding about the gene and the disease.
cancer (continued). "Degradation of NRF2 by GSK3/β-TrCP through AMPK/mTOR activation was enhanced in such cancer-specific ferroptosis." (PMID 34093872, 2021). "mTOR enhances cancer cell growth and proliferation, and mTOR inhibitors inhibit growth in a dose-dependent manner." (PMID 35008848, 2021). "mTOR inhibitors, such as rapamycin and everolimus, have been approved for the treatment of some types of cancers." (PMID 35372372, 2021). "Metformin can target the mTOR pathway by activating AMPK to inhibit tumorigenesis by decreasing cancer cell proliferation." (PMID 34235153, 2021). "Novel studies using powerful and refined methods of analysis have also shown that PI3K, along with Akt1 and the mTOR (mechanistic target of rapamycin) signaling pathway, is significantly more involved in cancer development than any other genes." (PMID 33338300, 2021). "Although a recent study showed that YAP1 mediates crosstalk between the Hippo and PI3K-TOR pathways by suppressing PTEN via miR-29, some PTEN-deficient cancer cells and tumour tissues also showed coactivation of the YAP and mTOR pathways." (PMID 34462427, 2021). "LINC01554 promotes proteasomal degradation of PKM2, an important enzyme at the late stage of glycolysis, and inhibits the Akt/mTOR signaling pathway, one of the key signalling pathways that mediates cellular biosynthesis and aerobic glycolysis in cancer cells." (PMID 33652661, 2021). "The development of immune checkpoint inhibitors, such as anti- programmed death ligand 1 (PD-L1) antibodies, has led to preclinical studies in mTOR-driven diseases, such as LAM, and combinations with mTOR/PI3K inhibitors in cancer." (PMID 33668092, 2021). "Remarkably, Myricetin, Apigenin and its derivative Vitexin, Luteolin, Eriotyctiol, Taxifolin, Naringenin, EGCG, and Cyanidin also decreased AKT phosphorylation and mTOR effectors in several cancer models, avoiding this feedback activation loop." (PMID 33918290, 2021). "The PI3K/Akt/mTOR pathway is frequently dysregulated in human cancers, and mTOR is the master regulator of this pathway that has a critical role in cancer and participate in cell transformation, growth, survival, and drug sensitivity." (PMID 34540820, 2021). "Altered expression of the components of PI3K-Akt-mTOR pathway has been reported with alterations in the m6A mRNA methylation or its regulators in different cancer types." (PMID 33814008, 2021). "Despite its complexity, the role of mTOR in cancer has led to different therapeutic strategies, including ‘rapalogs’—rapamacyin derivatives—which have shown efficacy in certain contexts." (PMID 34685734, 2021). "We designed an open-label phase II clinical trial to evaluate if the combination of everolimus (mTOR inhibitor) plus cisplatin (interferes with DNA function) will improve the rate of pathologic response, as assessed by residual cancer burden (RCB)." (PMID 33420229, 2021). "One of the mTOR complexes, mTORC1, which is frequently impaired in certain cancers, has been shown to be more sensitive to treatment with sirolimus than mTORC2, making sirolimus a potential anticancer treatment as well." (PMID 34065929, 2021). "The dysregulation of the PI3K–Akt–mTOR pathway is involved in the development of numerous human diseases, such as cancer." (PMID 34444753, 2021). "Three of them are dual PI3K/mTOR inhibitors, which induced micromolar toxicities on different cancer cell lines." (PMID 34500781, 2021). "Similar to rapamycin, targeting mTOR with kinase inhibitors potentiates the anti-cancer effects of checkpoint inhibitors." (PMID 33802831, 2021). "The PI3K/Akt/mTOR signaling pathway is frequently stimulated in various human cancers, contributing to the regulation of various processes of cancer development, such as metabolism, proliferation, apoptosis, chemoresistance, and genomic instability." (PMID 33920802, 2021). "Activated AKT, in turn, regulates downstream effectors including mammalian target of rapamycin (mTOR), often deregulated in human cancer." (PMID 34445095, 2021).
cancer (continued). "Activated p70S6K, which is mediated by the PI3K/AKT/mTOR axis, functions as an upstream regulator of Rac1 and Cdc42 that controls actin reorganization during cancer cell movement." (PMID 34279440, 2021). "AKT and mTOR are a well described modulatory signaling pathways that regulates cancer cells survival." (PMID 34402718, 2021). "Even with the use of consensus-based pathogenicity criteria to classify MTOR variants, it remains challenging to distinguish rare, benign population MTOR variants from pathogenic NDD- and cancer-associated variants." (PMID 34197453, 2021). "PD-L1 expression on cancer cells can engage with infiltrating immune effector cells that express PD-1, limiting activation of downstream mTOR signaling." (PMID 34512641, 2021). "The AMPK /mTOR pathway is an important pathway for the regulation of cell metabolism and plays an important role in cancer cells." (PMID 34604067, 2021). "By acting in PI3K/AKT/mTOR, a pathway with recognized importance in cancer, artemisinin was shown to be able to impair the migration, invasion, and proliferation of UM cells." (PMID 34931134, 2021). "The PI3K/AKT/mTOR signaling pathway plays a broad spectrum role in physiology, and its dysregulation often leads to multiple diseases, including cancer." (PMID 34088349, 2021). "Piceatannol shows an anti-cancer activity by exerting repressive effects on multiple cellular factors, such as mTOR and STAT3." (PMID 34575983, 2021). "The mammalian target of rapamycin (mTOR) is a protein kinase involved in the control of some determinant physiological pathways related to cancer processes, such as cell growth, proliferation, protein synthesis, metabolism, and autophagy." (PMID 33440795, 2021). "Studies have shown that p-mTOR is overexpressed in various tumors and is closely related to cancer metastasis and prognosis." (PMID 34221974, 2021). "However, little is known about the impact of NDD-associated MTOR missense variants on protein function or structure, how they may compare to cancer-associated variants, and whether the 3D properties of variants may enhance the accuracy of predicting pathogenicity." (PMID 34197453, 2021). "Knockdown of TFEB, the downstream transcription factor of mTOR, diminished radioresistance in cancer cells, indicating the involvement of lysosomal biogenesis in autophagy-dependent radioresistance." (PMID 33990205, 2021). "This review aims to present mTOR inhibitors and their effect on adaptive immunity and to discuss the anticancer potential of combining mTOR inhibitors with different modalities of cancer immunotherapy." (PMID 33802831, 2021). "Mostly through the activation of the PI3K/AKT/mTOR pathway, PTEN deficiency influences a variety of biologic processes that sustain cancer cell growth and proliferation." (PMID 34199293, 2021). "The feedback activation of STAT3 by PI3K/mTOR inhibitors raises the possibility that simultaneously targeting PI3K/mTOR and STAT3 activity in PTEN-deficient cancer cells can synergistically inhibit tumor progression." (PMID 33431808, 2021). "The ITGAV (integrin subunit alpha v) gene encodes integrin αv which activates several signaling pathways including MAPK and mTOR and regulates a wide range of cellular processes in cancer biology." (PMID 33718208, 2021). "Quercetin exerts its anti-cancer effects on different cancer cells through the regulation of PI3K/Akt/mTOR, Wnt-catenin, and MAPK/ERK1/2 pathways." (PMID 33746748, 2021). "To date, mTOR has gained wide interest in its potential therapeutic role in several proliferative diseases such as cancer." (PMID 33692478, 2021).
cancer (continued). "Studies have shown that the mammalian target of rapamycin (mTOR) also plays an important role in the regulation of cell migration, invasion, and cancer metastasis." (PMID 33530617, 2021). "Torkinib/PP242 is a selective ATP-competitive inhibitor of mTOR with promising anti-cancer activity over numerous cancer types." (PMID 33801030, 2021). "Reflecting its importance in physiological regulation, the PI3K/MTOR network is frequently disrupted in human diseases, including cancer, metabolic and neurodegenerative disorders." (PMID 34529665, 2021). "Signaling pathway analysis showed the involvement of cancer-related pathways, including mTOR (highlighted in blue), phosphoinositide 3-kinase/AKT, and Wnt/b-catenin pathways." (PMID 33893278, 2021). "PTEN acts on the phosphoinositide 3-kinase (PI3K)-AKT-mammalian target of rapamycin (mTOR) pathway and is one of the most commonly disrupted tumor suppressors in human cancer." (PMID 33557421, 2021). "The mTOR signaling pathway regulates cell metabolism, growth, proliferation, survival, and autophagy in many cancers; mTOR inhibitors suppress inflammation, proliferation, autophagy, and apoptosis and are used in cancer treatment." (PMID 34859058, 2021). "Quercetin exerts the anticancer effects by reducing cancer cell viability and enhancing apoptosis and autophagy through the modulation of Akt, mammalian target of rapamycin (mTOR), and HIF-1α signaling pathways." (PMID 33919512, 2021). "In cancer, the presence of UBE2O causes upregulation in the mTOR-HIF1a pathway, which is strongly correlated with pro-growth, glycolytic, and biosynthetic programs." (PMID 34451875, 2021). "Sirolimus and LY-294,002, as mTOR inhibitors, were found to target glycolysis in all 23 cancer types." (PMID 34304708, 2021). "As a result, the PI3K/mTOR pathway is an important target for cancer therapeutics, and a number of targeted drugs directed at this pathway have already been approved for clinical usage." (PMID 34203293, 2021). "Most of the adverse hematological effects of mTOR inhibitor use are reported by organ transplant recipients and cancer patients; however, similar effects have also been noted in TSC patients." (PMID 34202704, 2021). "On the other hand, high expression of DDIT4 can protect human cancer cells from hypoxia-induced cell death through stabilizing HIF1α in downstream of the suppressed mTOR pathway which followed by occurs increased cell survival and tumor growth." (PMID 34211002, 2021). "MELK is reported to be involved in multiple cellular events in tumorigenesis and malignant progression of human cancers by phosphorylation and regulation of several signaling molecules, such as NF-κB and mTOR." (PMID 33931086, 2021). "A promising alternative is to identify and target processes downstream of mTOR that are selectively required for cancer cell survival." (PMID 33318657, 2021). "M6A regulators clusterA was significantly enriched in biological processes, such as adhesion junctions, mTOR signaling, basal transcription factors and cancer-specific pathways." (PMID 34900988, 2021). "A rigorous mathematical model of the PI3K/Akt/mTOR signaling pathway would be invaluable in patient-specific therapy of many cancers." (PMID 33313340, 2021). "Inactivation of mTOR to restrain cancer cell proliferation was suggested as a promising strategy for the treatment of HCC." (PMID 34639131, 2021). "Hyperactivation of mTOR by amino acids in cancer cells is one of the hallmarks of the tumor progression, leading to rapid proliferation of cancer cells." (PMID 34003553, 2021).
cancer (continued). "By GSEA, we found that high expression of the five prognostic MRGs was more enriched in cancer and bacteria-induced infectious disease–related pathways, such as the glyoxylate and dicarboxylate metabolism pathway and mTOR signaling pathway." (PMID 35004676, 2021). "Unfortunately, faced with clinical data, either CDK4/6 or mTOR inhibitors are found to have clinical limitations as single agents in cancer therapy, as some patients develop clinical resistance." (PMID 35008317, 2021). "Two cardiac glycosides, lanatoside C and peruvoside, were reported recently to induce human cancer cell apoptosis through the PI3K/Akt/mTOR signaling pathway, and lanatoside C was also found to bind to the key signaling proteins, including PI3K and Akt." (PMID 34577146, 2021). "The upregulation of mTOR inhibits autophagy resulting in the stimulation of cancer growth and progression." (PMID 34760363, 2021). "PI3K/Akt/mTOR pathway is involved in cancer tumorigenesis, proliferation, and progression which makes this pathway crucial in cancer therapy." (PMID 33628319, 2021). "Currently, there are multiple ongoing clinical trials examining the efficacy of PI3K, Akt and mTOR inhibitors either in single or combination treatments with other drugs in different cancer settings." (PMID 34203293, 2021). "Everolimus (ELM) is a commonly used antagonist of mTOR that has shown tumor-suppressing functions in cancer management." (PMID 34540820, 2021). "Cancer therapy uses numerous drugs to inhibit the mTOR pathway, such as everolimus, temsirolimus, and ridaforolimus." (PMID 34361836, 2021). "ELM is a well-established mTOR inhibitor that has been suggested as an ideal combination regimen with chemotherapy for the management of cancers." (PMID 34540820, 2021). "mTOR is the master regulator of cellular metabolism, and its deregulation is closely related with cancer." (PMID 33417512, 2021). "This high ROS level stimulates cancer cell progression both by activating cell survival pathways (Akt, mTOR and NF-κB) and by stimulating angiogenesis related to hypoxia (HIF-1α)." (PMID 34827149, 2021). "In this review, we discuss the functioning of the mTOR signaling and autophagy in ESCs in detail that allows us to deepen our understanding of the biology of cancer cell dormancy." (PMID 34832087, 2021). "Prolonged mTOR inhibition can however lead to reactivation of cancer growth, stressing the need for further research to better understand the multifaceted impact of mTOR signaling on cancer progression." (PMID 34685734, 2021). "As mTOR and p-cofilin play an important role in the migration of cells and cancer cell metastasis, we exposed LAM cell to sirolimus to investigate its effect on cell viability, proliferation, and migration." (PMID 34445268, 2021). "This article summarizes the key progress made in this area and discusses the role of flavonoids by specifically inhibiting the PI3K/Akt/mTOR pathway in various cancers." (PMID 34830339, 2021). "Given the evidence that AMPK represses the mTOR pathway in cancer, we supposed there is a regulatory loop of miR-223-SIRT3-AMPK-mTOR-HIF-1α in CAF-mediated effect." (PMID 33819917, 2021). "In those studies, Rab1A was shown to be a mTOR activator and an oncogene, frequently overexpressed in human cancer (55, –, 57)." (PMID 34346699, 2021). "They seem to suppress MBC through dual anti-cancer effects (MTOR pathway inhabitation and angiogenesis suppression)." (PMID 33981594, 2021). "Although a large number of signaling molecules are associated with mTOR/ERK-1/2 signaling pathways, very few studies have reported their differential expression in different races of cancer patients." (PMID 33996789, 2021).
cancer (continued). "Logically, cancer cells, before committing to a dormant state, are obliged to have the similar to ESCs profile of the mTOR pathway, inhibition of which would allow entering diapause." (PMID 34832087, 2021). "ESCs, sharing their main features with cancer stem cells, have a delicate balance between the mTOR pathway and autophagy activity permissive for diapause induction." (PMID 34832087, 2021). "It is worth mentioning that hyperactivation of mTOR signaling represents one of the mechanisms responsible for chemoresistance in cancer, and its inhibition is exploited by chemotherapy drugs to exert their anti-tumor action." (PMID 34959348, 2021). "AKT/PI3K/mTOR signaling is commonly disrupted in human cancers, with AKT being a central component of the pathway, influencing multiple processes which are directly involved in tumorigenesis." (PMID 34853384, 2021). "The mTOR pathway, one of the most significant targets in modern cancer treatment, is triggered by growth factors and is responsible for cell survival, proliferation and angiogenesis." (PMID 34065268, 2021). "The PI3K/Akt/mTOR pathway is found deregulated in cancer, which is characterized by an overexpression/hyperactivation of its effector proteins and alterations in the genes that encode those proteins." (PMID 34744708, 2021). "In summary, mTOR plays major role in cell growth and proliferation, hence, it is a principal target in cancer therapy." (PMID 34535145, 2021). "PI3K/Akt/mTOR pathway, crucial for the proliferation, growth, and survival of tumor cells, is often overactivated in various cancers and it appears to be a potential target for anticancer therapy." (PMID 34073042, 2021). "The core components of this pathway, namely PI3Ks, AKT, and mTOR, have been extensively studied and found to be frequently hyperactivated in several human cancers, and their inhibition has been shown to lead to tumor regression in many preclinical studies." (PMID 34199959, 2021). "Pathway analysis showed that a large number of interacting proteins were involved in endocytosis, RNA transport, ER protein processing, ribosomes, EBV infection, proteoglycans in cancer, mTOR signaling and phagosomes." (PMID 33920772, 2021). "mTOR is a central regulator of multiple cellular processes promoting cancer cell growth, survival, and metastasis." (PMID 33479203, 2021). "Several anticancer drugs can induce apoptosis and autophagy through blocking the Akt/mTOR signaling pathway in various cancer cells." (PMID 33708631, 2021). "The serine/threonine kinase mechanistic target of rapamycin (mTOR) constitutes a key central regulator of metabolic pathways promoting cancer cell proliferation and survival." (PMID 34634301, 2021). "mTOR is a regulator of immune cell function and contributes to the high proliferation rate of cancer cells." (PMID 34206503, 2021). "mTOR is frequently hyperactivated in cancer, conferring cancer cells with proliferative and survival advantages over normal cells." (PMID 34634301, 2021). "Inhibition of the mTOR signaling pathway reduces the proliferation and anchorage-independent growth of cancer cells and glioma cells." (PMID 33482765, 2021). "The PI3K/AKT/mTOR signaling cascade is a major signaling pathway involved in cell proliferation and protein synthesis in a variety of cell types including cancer cells and PASMCs." (PMID 34408668, 2021). "Taken together, our findings identified a novel molecular mechanism involved in modulating mTOR activity and a previously unidentified potential pathway contributing to PTEN/PI3K/AKT-independent increase of mTOR activity observed in a subset of cancers." (PMID 34634301, 2021). "mTOR signaling is also involved in the reprogramming lipid, amino acids and nucleotide metabolism in cancer cells and immune cells to promote tumor cell progression and escape immunological surveillance." (PMID 34858835, 2021).